TNF (tumor necrosis factor)
Diseases named in the same sentence as TNF in open-access papers (continued):
Sharing a sentence is not in itself a finding about the gene and the disease.
dry eye (119 papers, 2005 to 2025). "Inflammation caused by postoperative dry eyes can increase the levels of inflammatory cytokines in tears, such as IL − 1a and IL-1b, TNF-a, IL-6, and IL-8, several of which play key roles in epithelial hyperproliferation and keratinization." (PMID 38259844, 2023). "In a parallel manner, the clinical severity of dry eye was associated with the concentrations of IL-17 and TNF-α in tears." (PMID 30096194, 2018). "Long-term dry eye is associated with increased expression of inflammatory factors, such as TNF-α, MMP-2, MMP-9, ICAM-1, and VCAM-1, on the ocular surface." (PMID 30002412, 2018). "To investigate the mechanisms underlying PM2.5-induced dry eye, we analyzed the activation of NF-қB and TNF-α by western blotting." (PMID 30546125, 2018). "In previous studies increased levels of ribonucleic acid transcripts encoding IL-1, IL-6, TGF-β1, and TNF-α and were detected in the conjunctiva of patients with keratoconjunctivitis sicca." (PMID 27695117, 2016). "Exploring molecular mechanisms of TNF-α generation via the TLR2–NF-κB signaling pathway should be quite useful for developing therapeutic approaches to combat dry eye associated with cGVHD." (PMID 22025895, 2011). "In conclusion, this is the first report to suggest that TLR2 and NF-κB expression is upregulated in dry eye associated with cGVHD and that this upregulation results in the significant generation of proinflammatory factor TNF-α." (PMID 22025895, 2011). "Long-term dry eye is associated with increased expression of inflammatory factors, such as tumor necrosis factor-alpha (TNF-α), matrix metalloproteinase (MMP-2, MMP-9), intercellular adhesion molecule-1 (ICAM-1), and vascular cell adhesion molecule-1 (VCAM-1) in the ocular surface." (PMID 30002412, 2018). "Clinical studies on dry eye patients reported an increase in pro-inflammatory cytokines and chemokines in tears and conjunctival cells such as interleukin (IL) -6, IL-8, TNF-α and IL-1β; a loss in conjunctival goblet cells; and an increase in immune activation and infiltration in the conjunctiva." (PMID 27486749, 2016). "While in control group, ocular surface parameters were correlated with IFN-γ, TNF-α, and GC-associated proteins, indicating that the aggravation of dry eye following conventional treatment may be related to goblet cell dysfunction and elevated levels of inflammatory mediators in tears." (PMID 40178682, 2025). "In a murine model of dry eye, these nanocomplexes significantly reduced inflammatory markers, including TNF-α, ICAM-1, VCAM-1, MMP-2, MMP-9, IL-17, IL-1β, and IL-6, thereby underscoring their therapeutic utility in DED." (PMID 41300436, 2025). "A study showed lowered levels of IL-1β, IL-6, and TNF-α in dry eye participants after treatment with topical cyclosporine tds." (PMID 40565378, 2025). "The RT-qPCR experiments demonstrated that the MSC-CM + Tβ4 treated group attenuated the expression of IL1β and TNF-α in the context of dry eye." (PMID 39837870, 2025). "The presence and extent of corneal damage can reflect the severity of dry eye, while elevated inflammatory factors such as IL-1β and TNF-α indicate increased ocular inflammation." (PMID 39403388, 2024). "For example, increases in the concentrations of inflammatory cytokines, such as IL-1B, Il-6, IL-8, and tumor necrosis factor-α (TNF-α), in tears are correlated with clinical indices of dry eye." (PMID 39596346, 2024).
dry eye (continued). "Immunofluorescent staining results also indicated an increase in inflammatory cytokines such as IL-1β, IL-6, and TNFα in the dry eye group, while the dry eye + LED group exhibited an overall significant decrease." (PMID 38139321, 2023). "The mRNA expression of miR-146a, TNF-α, IL-1β, IL-6 and IL-8 in the corneas of dry eye model mice was measured by real-time quantitative PCR (RT-qPCR)." (PMID 37433841, 2023). "TNFα and IL-1β were previously used inflammatory inducers in preclinical studies, including in vitro dry eye models." (PMID 36675083, 2023). "We aimed to investigate the role of microRNA-146a (miR-146a) in regulating corneal inflammation in a mouse model of benzalkonium chloride (BAC)-induced dry eye and the TNF-α-induced NF-κB signaling pathway in human corneal epithelial cells (HCECs)." (PMID 37433841, 2023). "Similar to the effects seen with DOPG, topical doxycycline in mouse models of dry eye reduces expression of IL-1α, IL-1β, and TNF-α, and in LPS-stimulated corneal epithelial cells, it has been shown to reduce IL-1β transcription and translation." (PMID 36982926, 2023). "Remarkably, we found that the levels of IL-6, IL-1β, and TNF-α increased in the corneas of dry eyes but significantly decreased after multi-wavelength LED treatment; these cytokines thus contribute to dry eye inflammation." (PMID 38139321, 2023). "IL-6, IL-1β, and TNF-α play important roles in ocular inflammation; dry eye increases the levels thereof." (PMID 38139321, 2023). "The expression levels of TNF-α and IL-1β in the DE-group were obviously higher than those in the C-group, indicating that TNF-α and IL-1β expression was induced during corneal inflammation in dry eye model mice." (PMID 37433841, 2023). "Vitamin C likely acts as a non-enzymatic antioxidant and anti-inflammatory agent that appears to be effective in alleviating dry eye by downregulating TNF-α-induced ICAM-1 expression via the inhibition of NF-κB activation." (PMID 35887783, 2022). "Topical administration of MSCs has been shown to significantly decrease CD4, IL-1, IL-6, and tumor necrosis factor-alpha (TNF-α) levels in dogs affected by keratoconjunctivitis sicca." (PMID 36290184, 2022). "TNF-α is significantly increased in the tears of dry eye patients as one of the most common pro-inflammatory cytokines." (PMID 35360713, 2022). "Researchers have also shown a significant increase in the expression of IL-6 and TNF-α in the tear fluid of the dry eye patients with MGD when compared with dry eye patients without MGD." (PMID 35685417, 2022). "Once the NF-κB signaling pathway is inhibited, the expression of IL-1β, TNF-α, and IL-6 on the ocular surface of dry eye, as well as the activation of immune cells, can be down-regulated." (PMID 35812407, 2022). "For instance, in dry eye syndrome, this approach can inhibit inflammatory cytokines such as TNF-α and Il-1β." (PMID 35943663, 2022). "Generally frequent and less serious pathologies (dry eye, blepharitis with anti-TNF use) can significantly alter patients’ quality of life." (PMID 35956153, 2022). "Inflammatory cytokines, such as interferon-1 (IL-1) produced mainly by Th1 cells and TNF-α produced mainly by Th17 cells, are elevated in the cornea and conjunctiva of dry eye." (PMID 35360713, 2022). "Kaempferol can promote tear production and corneal repair by inhibiting proinflammatory factors such as IL-1B, IL-6, IL-8, and TNFα and has significant therapeutic effects in rabbit dry eye models." (PMID 36590763, 2022). "Tear-derived inflammatory biomarkers include tumor necrosis factor alpha (TNF-α), interleukin 6 (IL-6), IL-8, and IL-17, which are all elevated in dry eyes." (PMID 35886858, 2022). "It has been shown that dry eye-related inflammatory mediators (TNFα, IL-1β, IL6/IL17, and prostaglandin E2) upregulate MUC5AC mRNA expression." (PMID 36209216, 2022).
dry eye (continued). "The areas under the curves of IL-1, IL-6, and TNF-α were 0.801, 0.800 and 0.736, respectively, indicating that IL-1, IL-6, and TNF-α in tears of patients with xerophthalmia have a high predictive value in efficacy." (PMID 35130850, 2022). "qPCR analysis revealed that the mRNA levels of TNF-α, IL-1β, and IL-6 in dry eyes were significantly up-regulated by 3.0, 2.6, and 3.3-fold, respectively, compared to the NS mice." (PMID 34445121, 2021). "Previous clinical studies on inflammatory mediators that occur in dry eye disease have shown elevated levels of IL-1β, IL-8, and TNF-α in the tear film of dry eye patients." (PMID 33921231, 2021). "In cornea and conjunctiva of normal or dry eye model mice, the mRNA expression levels of IL-1β, IL-6, IL-8, TNF-α, IFN-γ, and MMP-9 were investigated by real-time PCR in the presence or absence of isorhamnetin." (PMID 33921231, 2021). "Significant differences in the concentration of cytokines (IL-6, IL-10, and TNF-α) were detected in tear samples collected from patients with dry eyes." (PMID 34659636, 2021). "In this study, we selected several inflammatory cytokines associated with dry eye, including IL-17A, IL-10, IL-12p70, INF-γ, IL-6, and TNF-α." (PMID 34659636, 2021). "TNF-α and IL-6 are important factors of goblet cell apoptosis and dry eye symptoms in patients with concomitant exotropia." (PMID 34659636, 2021). "The most widely studied pro-inflammatory cytokine accompanying dry eye is Interleukin (IL)-1 alongside IL-6, IL-8, IL-1β and TNFα which is also known to play a significant role in DES-related inflammation." (PMID 32629860, 2020). "Disruption of the tear film can lead to dry eye syndrome and can also induce inflammatory factors, including TNF-α and IL-6." (PMID 32674521, 2020). "Inflammation mediated by pro-inflammatory cytokines such as tumor necrosis factor-alpha (TNF-α), interleukin (IL)-6, and IL-8 is high in tears of dry eye patients." (PMID 33036453, 2020). "Increase in IL-1β and TNF-α levels in the basal epithelium of diabetic patients with dry eye has been reported." (PMID 32437405, 2020). "It triggers autophagy in cultured corneal epithelial cells to restore cellular homeostasis in response to inflammatory cytokines interferon-γ and tumor necrosis factor, which are both sources of stress in dry eye." (PMID 31950044, 2019). "Dry eye patients were found with higher levels of proinflammatory cytokines such as IL1α along with IL-1β, IL-6, IL-8, and tumor necrosis factor (TNF-α) in the tear film compared to normal controls." (PMID 30519584, 2018). "Expression of interleukin 6 (IL-6) and TNFα is upregulated by local tissue dryness in conjunctiva of dry eye patients and experimental dry eye model." (PMID 26818460, 2015). "In the dry eye model of rats, the IL-6 and TNFα mRNA level in the cornea measured by real-time RT-PCR increased." (PMID 26818460, 2015). "Proapoptotic cytokines such as TNF-α and IL-1 have been detected in conjunctival epithelium and tear fluid of dry eye patients, and also increased in our airlift culture system." (PMID 24498087, 2014). "It was seen that the tear levels of TNF-alpha increases in various inflammatory pathologies of the ocular surface (such as Sjogren's syndrome, rosacea, and dry eye)." (PMID 24259948, 2013). "After desiccation, the corneas of the dry eye model rat were collected to isolate total RNA and the levels of expression of IL-6 and TNF-α were determined by TaqMan real-time PCR." (PMID 21976951, 2011). "TNF-α mRNA levels were elevated in the patients with dry eye related to cGVHD (3.05±2.95 versus 0.99±0.40, p<0.001)." (PMID 22025895, 2011). "In the dry eye model rats, the IL-6 mRNA level in the cornea significantly increased, whereas TNF-α mRNA level slightly increased." (PMID 21976951, 2011). "Dry eye stimulated the expression of TNF-α and MMP-9, and activated the MAPK signaling pathway on the ocular surface in the dry eye mouse model." (PMID 21976951, 2011).
dry eye (continued). "In our previous reports using the botulinum toxin B-induced murine dry eye model, TNF-α and IL-1β were increased on both the ocular surface and lacrimal gland, whereas MIF was increased only in the lacrimal gland." (PMID 21152395, 2010). "Increased levels of multiple cytokines including interleukin-6 (IL-6), interleukin-8 (IL-8), and tumor necrosis factor-alpha (TNF-α) have been detected in both the tear fluid of patients with dry eye symptoms and also in animal models of the disease." (PMID 20824100, 2010). "In the multifactorial dry eye syndrome, there appears to be increased production of proinflammatory cytokines such as interleukin-1 (IL-1), interleukin-6 (IL-6), interleukin-8 (IL-8), tumor necrosis factor-alpha (TNF-α), and proteolytic enzymes." (PMID 19753313, 2009). "Given that proinflammatory cytokines such as IL-1β, IL-6, IL-8, IL-10, interferon-γ (IFN-γ), and tumor necrosis factor-α (TNF-α) are elevated in dry eye patients under hyperosmotic conditions, curcumin emerges as a promising alternative therapeutic agent for DED." (PMID 41300436, 2025). "Consistent with our results, a recent research found that artificial tears combined with CsA could downregulate the TNF-α level in tear of dry eye patients, supporting the effect of CsA on ocular surface inflammation." (PMID 40178682, 2025). "TNF-α, IL-1β, and IL-6 are major markers of ocular surface inflammation in dry eye." (PMID 38399289, 2024). "Acupuncture may induce tumor necrosis factor levels which may play an important role in the treatment of dry eye." (PMID 39195191, 2024). "Studies have shown elevated levels of various cytokines, including interleukins (ILs)-1, 4, 8, 10, 17A, and 6; matrix metalloproteinase (MMPs)-3 and 9; tumor necrosis factor-beta (TNF-β); and tumor necrosis factor-alpha (TNF-α) in dry eye patients, and their levels correlate with disease severity." (PMID 38247916, 2023). "Furthermore, treatment with TNF inhibitors improved conjunctival goblet cell numbers in RA patients with mild dry eye, which is conducive to relieving dry eye by increasing the secretion of mucin." (PMID 37238594, 2023). "Earlier studies have shown that alterations of the tear cytokine profiles occur in DED patient, with elevated proinflammatory cytokine levels such as IL-1, IL-6, IL-8, and TNF-α shown to be strongly correlated with dry eye markers, leading to ocular surface damage and goblet cell reduction." (PMID 37771976, 2023). "Contradictory data exists in the literature regarding anti-TNF use and dry eye." (PMID 35956153, 2022). "Other studies have shown that an TNF-α blocker had an antiapoptotic effect on human salivary gland epithelial cells which is a significant pathological environment for SS, and suppressed inflammation in the lacrimal gland and cornea in dry eye treatment." (PMID 35990826, 2022). "We found that the phosphorylation of ERK and the expression of AQP5 were significantly elevated in the hyperosmotic-condition-induced dry eye cell model, as well as the inflammatory IL-6, IL-8 and TNF-α, which promote the inflammatory response and apoptosis of cells." (PMID 36232498, 2022). "In addition, receiver operating characteristic curves were drawn to analyze the predictive value of IL-1, IL-6, and TNF-α in efficacy on xerophthalmia." (PMID 35130850, 2022). "The level of TNF-α significantly increased at 1 month (p = 0.031) and returned to the baseline level at 3 months postoperatively in subjects with dry eye; at 6 months postoperatively, the levels of IL-6 and IL-8 declined slightly but were still higher than the baseline levels (p = 0.004, p = 0.047)." (PMID 34957146, 2021). "A significant increasing trend of interleukin (IL)-6 was found in both dry eye and subjects without preexisting dry eye (p = 0.016, p = 0.008), while IL-8 and tumor necrosis factor alpha (TNF-α) were only found to be increased in subjects with dry eye postoperatively (p = 0.031, p = 0.031)." (PMID 34957146, 2021).
dry eye (continued). "The production of TNF-α and IL-1 leads to the damage of dry eye surface in mice." (PMID 34659636, 2021). "Likewise, the beneficial role of this carotenoid in dry eye treatment was confirmed in human corneal epithelial cells via reduction in TNF-α and IL-1β levels." (PMID 34677429, 2021). "On the other hand, ATX has been shown to have anti-inflammatory effects in a mouse model of hyperosmoticity-induced dry eye due to suppression of TNF-α and IL-1β, as well as down-regulation of high-mobility group box 1, a proinflammatory marker involved in ocular damage." (PMID 34677429, 2021). "In addition, isorhamnetin significantly reduced ocular surface damage and expression of interleukin (IL)-1β, IL-8, and tumor necrosis factor (TNF)-α in an experimental mouse model of dry eye." (PMID 33921231, 2021). "One possible mechanism of light therapy may be the neutralization of TNF alpha and thus a reduction in ocular surface inflammation in dry eye patients." (PMID 34198493, 2021). "Particularly, treatment with ALA in cultures of corneal epithelial cells and when it is topically applied to a dry eye animal model has anti-inflammatory activity, decreasing the release and expression of inflammatory factors (TNF-a, IL-6, IL-1β, and IL-8) regulated by the NF-κB pathway." (PMID 31137826, 2019). "Studies by Pflugfelder and others have shown that the concentrations of inflammatory cytokines such as IL-1a, IL-6, IL-8 and TNF-α are increased in the conjunctival epithelium of patients with Sjögren syndrome, which is characterized by severe dry eye symptoms." (PMID 30096194, 2018). "It has been reported that TNF-α levels are elevated in tears of patients with dry eye syndrome." (PMID 25211490, 2014). "Therefore, we examined levels of TNF-α mRNA and protein secretion in patients with dry eye related to cGVHD and controls." (PMID 22025895, 2011). "Furthermore, in the cornea of the dry eye rat model, TNF-α slightly increased, which supported our in vitro data." (PMID 21976951, 2011). "Some preliminary trials have tried to regulate the inflammation of dry eye by neutralizing TNF-α." (PMID 22025895, 2011). "It appears that severe dry eye may benefit by down regulating TNF." (PMID 15985164, 2005). "Among these biomarkers, the inflammatory cytokine tumor necrosis factor-alpha (TNF-α) is a key indicator for ocular surface disorders, particularly dry eye syndrome (DES)." (PMID 41149298, 2025). "0.05% CsA alleviated dry eye related symptoms, suppressed expression of IFN-γ and TNF-α, and preserved goblet cell function as well as mucin production." (PMID 40178682, 2025). "Nitric oxide synthase, cyclooxygenase-2, TNF-α, phospholipase D, phospholipase A2, NF-kB, and MAPK, which ultimately leads to dry eye." (PMID 39403388, 2024). "Significant increase in the infiltration of inflammatory cells on the ocular surface and the release of tumor necrosis factor-α (TNF-α), interleukin-1β (IL-1β), and so on was found in the patients with dry eye." (PMID 39403388, 2024). "Dry eye is accompanied by inflammation with increased levels of inflammatory and T cell-related mediators such as IL-1β, IL-6, TNF-α, IL-17, and IFN-γ, noted in the conjunctiva and tear fluid of dry eye patients." (PMID 36830827, 2023). "The expression of inflammatory factors such as IL-1β, IL-6, IL-8, TNF-a and IFN-γ and infiltrated inflammatory cells, has been shown to be increased on the ocular surface of dry eye patients." (PMID 35812407, 2022). "The phosphorylation of NF-KB was reduced along with a decrease in TNF-α, IL-1β, and IL-6 in BAC-induced dry eye mice following treatment with KIOM-2015E." (PMID 36499298, 2022). "In summary, we found that high expression levels of inflammatory factors (IL-6, and TNF-α) in tears of patients with concomitant exotropia were significant higher than the control, which could be a potential factor who promoted the occurrence of dry eye in the patients with concomitant exotropia." (PMID 34659636, 2021).